GGT5 (gamma-glutamyltransferase 5)
Diseases named in the same sentence as GGT5 in open-access papers (continued):
Sharing a sentence is not in itself a finding about the gene and the disease.
lung adenocarcinoma (6 papers, 2020 to 2024). A carcinoma that arises from the lung and is characterized by the presence of malignant glandular epithelial cells. "Another study in lung cancer has shown that the gene GGT5 is highly expressed in cancer-associated fibroblasts (CAFs) in lung adenocarcinoma, and high levels of GGT5 contribute to the survival and drug resistance of cancer cells in CAFs." (PMID 35257007, 2022). "One study showed that GGT5 is highly expressed in cancer-associated fibroblasts (CAFs) derived from lung adenocarcinoma tissues, and contributes to cancer cell survival and drug resistance." (PMID 36090054, 2022). "In this study, we found that gene GGT5 was highly expressed in cancer-associated fibroblasts (CAFs) in lung adenocarcinoma, predicting the unfavorable survival of patients with lung adenocarcinoma." (PMID 32640421, 2020). "The application of GGsTOP, a remarkably selective and potent irreversible inhibitor of GGT activity, can markedly lower the expression of GGT5, hinder the proliferation and chemotherapy resistance of lung adenocarcinoma cells." (PMID 38748299, 2024). "Wei’s findings suggest that heightened GGT5 levels in cancer-associated fibroblasts (CAFs) contribute to cancer cell survival and drug resistance, indicating GGT5’s potential as a therapeutic target in lung adenocarcinoma." (PMID 38581025, 2024). "A recent study showed that for lung adenocarcinoma (LUAD), GGT5 was specifically highly expressed in cancer-associated fibroblasts instead of the tumor cells, which was proven to contribute to accelerating tumor cell proliferation and drug resistance in LUAD." (PMID 35368661, 2022). "Taken together, our study illuminates that high level of GGT5 in CAFs contributes to cancer cell survival and drug resistance, indicating that GGT5 may be a promising therapeutic target in lung adenocarcinoma." (PMID 32640421, 2020). "The results indicated that the expression level of GGT5 was significantly elevated in esophageal carcinoma (ESCA), glioblastoma multiforme (GBM), head and neck squamous cell carcinoma (HNSC), lung adenocarcinoma (LUAD), prostate adenocarcinoma (PRAD), and stomach adenocarcinoma (STAD) (p < 0.05)." (PMID 35368661, 2022).
lung carcinoma (5 papers, 2020 to 2025). "Wei and coworkers discovered that GGT5 was highly expressed in cancer-associated fibroblasts in lung cancer, predicting the poor survival of patients with lung cancer." (PMID 34513707, 2021). "First, Disease Ontology analysis of GGT5 in human using Coexpedia indicated that GGT5 was closely associated with malignant cancer development, including lung cancer." (PMID 32640421, 2020). "One study showed that GGT5 was helpful to make tumors get bigger and resisted drug performance in lung cancer." (PMID 35257007, 2022).
breast carcinoma (3 papers, 2022 to 2025). "However, GGT5 acts as a tumor suppressor in hepatocellular carcinoma, breast cancer, and clear cell renal cell carcinoma." (PMID 41316810, 2025).
glioma (3 papers, 2023 to 2024). A benign or malignant brain and spinal cord tumor that arises from glial cells (astrocytes, oligodendrocytes, ependymal cells). "Therefore, the elevation of GGT5 expression can be considered characteristic for gliomas." (PMID 36765904, 2023). "We also explored the perturbation effects of these genes which suggested that the importance of DPEP1, G6PD, GGT1, GGT5, IDH1, and NFE2L2 for glioma cell survival." (PMID 38819225, 2024). "GGT5 expression is upregulated in GBM and lower grade gliomas." (PMID 36765904, 2023).
stomach adenocarcinoma (3 papers, 2022 to 2024). "In this study, we aimed to evaluate the value of GGT5 in stomach adenocarcinoma (STAD)." (PMID 35257007, 2022).
melanoma (2 papers, 2020 to 2022). A malignant, usually aggressive tumor composed of atypical, neoplastic melanocytes. "The results showed that overexpression of GGT5 might be involved in cancer-related pathways, such as JAK-STAT and MAPK signaling pathway, leukocyte transendothelial migration, and melanoma." (PMID 35257007, 2022). "GSEA suggests that overexpression of GGT5 may be involved in leukocyte transendothelial migration, JAK-STAT signaling pathway, MAPK signaling pathway, and melanoma." (PMID 35257007, 2022). "Overexpression of GGT5 might be involved in cancer-related pathways, such as signaling pathway of JAK-STAT, as well as transendothelial migration of leukocyte, melanoma, and MAPK signaling pathway." (PMID 35257007, 2022). "The results showed that overexpression of GGT5 might be involved in signaling pathway of JAK-STAT leukocyte, as well as MAPK, transendothelial migration, and melanoma pathway." (PMID 35257007, 2022).
skin cutaneous melanoma (2 papers, 2022 to 2024). "Additionally, GGT5 exhibited heightened expression in HPV-HNSC- and SKCM (skin cutaneous melanoma) metastasis (p < 0.05)." (PMID 38581025, 2024). "Furthermore, GGT5 was highly expressed in HPV-HNSC+ and SKCM (skin cutaneous melanoma) metastasis." (PMID 35257007, 2022).
acute myeloid leukemia (1 paper, 2024). Acute myeloid leukemia (AML) is a group of neoplasms arising from precursor cells committed to the myeloid cell-line differentiation. "The findings revealed a positive relationship between elevated GGT5 expression and immune checkpoint-related genes in most cancer types, particularly in STAD, excluding thymoma (THYM), PCPG, acute myeloid leukemia (LAML), KICH, and bladder urothelial carcinoma (BLCA)." (PMID 38581025, 2024).
asthma (1 paper, 2024). "GGT5, a γ-glutamyl leukotrienes, can metabolize LTC4 to LTD4, making it a key player in the active role of asthma pathogenesis and indicating that it serves a significant role in the immune response." (PMID 38748299, 2024).
colorectal adenocarcinoma (1 paper, 2025). The most common type of colorectal carcinoma. "Potential diagnostic transcripts may include ADH1C, GGT5, NQO2, and SLC25A5 in colorectal adenocarcinoma." (PMID 41465541, 2025).
colorectal cancer (1 paper, 2025). A primary or metastatic malignant neoplasm that affects the colon or rectum. "Increased expression of GGT5 mRNA was found for breast, gastric, and colorectal cancer tumors in comparison to normal tissues." (PMID 41465541, 2025).
endothelial dysfunction (1 paper, 2025). In vascular diseases, endothelial dysfunction is a systemic pathological state of the endothelium (the inner lining of blood vessels) and can be broadly defined as an imbalance between vasodilating and vasoconstricting substances produced by (or acting on) the endothelium. "Given that oxidative stress and endothelial dysfunction are pivotal mechanisms underlying the progression of heart failure and other CVDs, it is plausible that GGT5 exerts a protective role in the cardiovascular system." (PMID 41472876, 2025). "Dysregulation among these nodes—characterized by reduced PLA2G2A and GGT5 expression together with elevated CYP2J2 and EPHX2—may reflect a disrupted AA-EET axis that favors oxidative stress, endothelial dysfunction, and maladaptive cardiac remodeling, ultimately contributing to HF progression." (PMID 41472876, 2025).
heart failure (1 paper, 2025). Inability of the heart to pump blood at an adequate rate to meet tissue metabolic requirements. "Four key biomarkers for heart failure with high diagnostic accuracy were recognized: GGT5, PLA2G2A, EPHX2, and CYP2J2." (PMID 41472876, 2025).
Hernia (1 paper, 2017). "GGT-4 is applied to failure of spleen to control circulating blood caused by spleen-Yang deficiency in Xue-lun-zheng by Rongchuan Tang; and GGT-5 has specific effects and great power for a variety of hernia symptoms and diarrhea in Shan-qi-zheng-zhi-lun by Japanese scholar." (PMID 28588638, 2017).
Hypertension (1 paper, 2018). The presence of chronic increased pressure in the systemic arterial system. "We have also identified 8 important genes (NME4, PNPLA7, GGT5, PTGS2, IGF1R, NT5C2, ENTPD1 and PTEN), a number of gene ontology categories and biological pathways that may be associated with military pilot hypertension." (PMID 29996846, 2018). "We have also identified 8 important genes (NME4, PNPLA7, GGT5, PTGS2, IGF1R, NT5C2, ENTPD1 and PTEN), a few GO categories and biological pathways that may be associated with the military pilot hypertension." (PMID 29996846, 2018). "The results from Western blotting showed that NME4 and PNPLA7 these two genes were up-regulated significantly and GGT5, PTGS2, IGF1R, NT5C2, ENTPD1 and PTEN these six genes were down-regulated significantly in PBMCs of military pilots with hypertension." (PMID 29996846, 2018).
idiopathic pulmonary fibrosis (1 paper, 2020). Idiopathic pulmonary fibrosis (IPF) is a nonneoplastic pulmonary disease that is characterized by the formation of scar tissue within the lungs in the absence of any known cause. "GEO public cohort analysis indicated that gene GGT5 was high expressed in lung tissues from patients with idiopathic pulmonary fibrosis, a lethal disorder characterized by the aberrant accumulation of fibroblasts and myofibroblasts, than that in normal lung tissues." (PMID 32640421, 2020).
lymph node metastasis (1 paper, 2024). "Univariate regression analysis revealed factors influencing overall survival (OS), including GGT5 expression, tumor location (Other sites vs. Antrum), tumor size, lymph node metastasis, and TNM stage (all p < 0.05)." (PMID 38581025, 2024).
myocardial infarction (1 paper, 2021). Gross necrosis of the myocardium, as a result of interruption of the blood supply to the area, as in coronary thrombosis. "Gamma-glutamyltransferase-5 (GGT5) is confirmed to be closely associated with immune cell activation and oxidative stress and can be a potential biomarker of myocardial infarction." (PMID 33509101, 2021).
neuroblastoma (1 paper, 2024). Neuroblastoma (NB) is the most common solid, extracranial childhood tumor. "Upregulated mRNAs, including SKA3, PLOD2, VIPR2, and GGT5, are implicated in neuroblastoma." (PMID 38892402, 2024).
non-small cell lung carcinoma (1 paper, 2020). A group of at least three distinct histological types of lung cancer, including non-small cell squamous cell carcinoma, adenocarcinoma, and large cell carcinoma. "Studies have confirmed that GGT5 gene amplification contributes to non-small cell lung cancer (NSCLC)." (PMID 32920549, 2020).
Parkinson disease (1 paper, 2025). A progressive degenerative disorder of the central nervous system characterized by loss of dopamine producing neurons in the substantia nigra and the presence of Lewy bodies in the substantia nigra and locus coeruleus. "Furthermore, GGT5 displayed positive enrichment in three pathways, including cytokine cytokine receptor interaction, complement and coagulation cascades, and hematopoietic cell lineage, and negative enrichment in two pathways, including oxidative phosphorylation and Parkinsons disease." (PMID 41472876, 2025).
prostate carcinoma (1 paper, 2025). A carcinoma that arises from epithelial cells of the prostate gland. "In conclusion, GGT1/GGT5 expression was upregulated but GGT6/GGT7 expression was downregulated in primary prostate cancers." (PMID 40094020, 2025). "Our results showed very strong negative correlations between the expression levels of GGT1/GGT5/GGT6 genes, and their DNA methylation levels in prostate cancer tissues." (PMID 40094020, 2025).
renal oncocytomas (1 paper, 2017). "All identified enzymes were basically unchanged, except gamma-glutamyl transpeptidase 1 and 5 (GGT1, 50-fold; GGT5, 15-fold), which were significantly down-regulated in renal oncocytomas." (PMID 29285300, 2017).
tuberculosis (1 paper, 2016). A chronic, recurrent infection caused by the bacterium Mycobacterium tuberculosis. "To determine which protein would be much relevant in response to clinical tuberculosis, we analyze the expression of GGT5 and CD13 in circulating monocytes from patients with active tuberculosis." (PMID 26957948, 2016). "By contrast, the expression of GGT5 in circulating monocytes from patients with active tuberculosis was decreased, which was not compatible to the data seen in proteomic analysis (unpublished observations)." (PMID 26957948, 2016).
tumor (15 papers, 2018 to 2025). "GGT5 is implicated in expediting tumor advancement by enhancing the proliferation and migration of GC cells through the modulation of EMT-associated pathways." (PMID 38581025, 2024). "Our analysis revealed that higher GGT5 expression and advanced tumor stage were linked to increased enrichment of memory CD8+ T cells." (PMID 38748299, 2024). "However, GGT5 expression was increased along with tumor stage progression and associated with worse progression-free survival." (PMID 40094020, 2025). "Fourth, As mutation-induced genomic instability, chromosomal deletions and rearrangements may cause the formation of tumor, so we explored the mutations of GGT5 in GC." (PMID 38581025, 2024). "In conclusion, GGT5 may serve as a promising prognostic biomarker and a potential immunological therapeutic target for GC, since it is associated with immune cell infiltration in the tumor microenvironment." (PMID 35368661, 2022). "Our findings demonstrated that memory CD8+ T cells, including TCM and TEM, were more abundant in the group with higher GGT5 expression and in the higher tumor stage group." (PMID 38748299, 2024). "In our investigation, pan-cancer analysis bioinformatics indicated heightened GGT5 expression in numerous tumor tissues, including GC tissues, compared to normal tissues." (PMID 38581025, 2024). "In tumor metabolism, GGT5 exhibits catalytic activity in both hydrolysis and transpeptidation reactions." (PMID 38748299, 2024). "In our study, the GC samples were classified into high/low groups based on the optimal cutoff value of GGT5 and subsequently analyzed for tumor heterogeneity between the two groups." (PMID 38748299, 2024). "RAB25 and GGT5 expression progressively decreased from normal tissue to tumor to thrombus, suggesting they consistently exert suppressive roles in both tumorigenesis and invasion." (PMID 37328520, 2023). "Combining the results of Wang’s and our own datasets revealed progressive downregulation of RAB25 and GGT5 from normal tissue to tumor to thrombus, suggesting their consistent suppressive roles in the development of both thrombi and tumors." (PMID 37328520, 2023). "GGT5 was highly expressed in the STAD tumor tissues compared to adjacent normal tissues, and correlated with worse DFS and OS, in line with previous studies." (PMID 36090054, 2022). "To evaluate the difference of GGT5 between diverse tumor and common cases, according to to TIMER2.0, we made a difference in expression results in the performance of TCGA." (PMID 35257007, 2022). "In this study, it is found that, compared with normal tissues, GGT5 had a high expression in many tumor tissues." (PMID 35257007, 2022). "Subsequently, we used Wilcoxon-rank-sum test to detect the expression of GGT5 in tumor tissues and normal tissues in three GEO data sets." (PMID 35257007, 2022). "Compared to adjacent normal tissues, expression of GGT5 was significantly elevated in STAD tumor tissues." (PMID 36090054, 2022). "Studies have shown that M2 macrophages are related to tumor progression, which explains why the high-expression GGT5 group has a worse prognosis." (PMID 35257007, 2022). "Taken together, our study illuminates that high level of GGT5 in CAFs contributes to tumor cell survival and drug resistance by increasing intracellular GSH and reducing the intracellular ROS level in LUAD cells." (PMID 32640421, 2020). "Results indicated that down-regulation of GGT5 in CAFs attenuated the growth of tumor cell in vitro." (PMID 32640421, 2020). "Consistent with these biostatistics, IHC staining also showed the increased protein levels of GGT5 in clinical LUAD samples than that in the paired non-tumor tissues." (PMID 32640421, 2020). "In tumor microenvironment, high levels of cysteine and glutamate in tumor microenvironment indicated that extracellular GSH was cleaved by CAFs-derived GGT5." (PMID 32640421, 2020).
tumor (continued). "These in vitro data suggest that CAFs-derived GGT5 promotes the transfer of GSH into LUAD cells from tumor microenvironment, which further reduces the intracellular ROS level in LUAD cells." (PMID 32640421, 2020). "First, inhibiting GGT5 activity with GGsTop (i.p. injection, 1 mg/kg) markedly suppresses the tumor growth in nude mice xenograft model in A549 and LAC1 cells and does not affect the body weight of mice." (PMID 32640421, 2020). "GGT5 contributes to tumor development by participating in a variety of signaling pathways, acting on immune cell infiltration in the tumor microenvironment, and regulating the metabolism of tumor cells." (PMID 41316810, 2025). "Furthermore, the correlation between GGT5 and clinical–pathologic characteristics, including histologic grade, tumor stage, T stage, N stage, and M stage, was measured." (PMID 38748299, 2024). "Furthermore, GGT5 overexpression in the tumor tissues was positively correlated with PD-L1 expression and CD8+ T cell infiltration." (PMID 36090054, 2022). "Gamma-glutamyltransferase 5 (Ggt5) promotes tumor growth in the lung." (PMID 35565312, 2022). "According to the results of pan-cancer analysis, we found great heterogeneity in the expression levels of GGT5 among various tumor types, which indicated that GGT5 might play different roles in different tumors." (PMID 35368661, 2022). "Our further study proved that CAFs in LUAD microenvironment were GGT5-positive, which indicated that GGT5 might mediate the crosstalk between tumor cells and CAFs." (PMID 32640421, 2020). "Moreover, our previous data of IHC staining also showed that GGT5-positive cells was specifically deposited in tumor stroma in clinical LUAD tissue sections." (PMID 32640421, 2020). "Hence, we further explored the influence of GGT5 blocking with GGsTop on tumor growth and chemosensitivity in mouse xenograft model." (PMID 32640421, 2020). "Therefore, our data revealed a novel crosstalk mechanism mediated by GGT5 between tumor cells and CAFs during cancer progression and treatments." (PMID 32640421, 2020). "In mouse xenograft model, we proved that targeting GGT5 with a small-molecule inhibitor GGsTop could inhibit tumor growth and increase the chemosensitivity of cancer cells." (PMID 32640421, 2020). "In this study, we confirmed that blocking GGT5 with a small-molecule inhibitor GGsTop could inhibit tumor growth and increase the drug-sensitivity of LUAD cells in mouse xenograft tumor model." (PMID 32640421, 2020). "Analysis results showed that GGT5 was significantly related to cell differentiation and cell cycle regulation, hinting that GGT5 might mediate the crosstalk between CAFs and tumor cells." (PMID 32640421, 2020). "Therefore, GGT5 may exert a pro-tumor effect by regulating immune genes such as CXCL12 and CXCL4 in the tumor microenvironment." (PMID 38748299, 2024). "We thought that GGT5 might be a new marker to judge tumor prognosis." (PMID 35257007, 2022). "Therefore, our results suggest that the poor prognosis in the GGT5-high expression group might be attributed to an imbalance in the immune function homeostasis and an impaired anti-tumor immune response." (PMID 35368661, 2022). "Moreover, foci formation in monolayer culture and spheres formation in soft agar analyses also suggested that interfering GGT5 expression in CAFs could inhibit tumor cell proliferation in vitro." (PMID 32640421, 2020). "Subsequent cross-analysis with the GTEx database unveiled elevated GGT5 levels exclusively in GBM, HNSC, and STAD tumor tissues (p < 0.05), aligning with the downregulated GGT5 tumors observed in the TCGA database." (PMID 38581025, 2024). "All of these methods to explore the immune infiltration mode of tumor microenvironment show consistent trend; the CD8+ T cells were observed to have significantly higher expression levels in the GGT5 high expression group." (PMID 38748299, 2024).